TLR3 (toll like receptor 3)
Diseases named in the same sentence as TLR3 in open-access papers (continued):
Sharing a sentence is not in itself a finding about the gene and the disease.
infection (continued). "Of the TLRs measured, only the mRNA expression levels of TLR3 were significantly altered post-infection, with levels increasing with time post-infection at both MOI." (PMID 25884204, 2015). "Many recent reports have demonstrated that host TLR3 plays an important role in the process of antiviral infection." (PMID 26634454, 2015). "Infection in bone marrow chimeric mice showed that TLR3-expressing hematopoietic cells are required for effective CHIKV clearance." (PMID 25452586, 2015). "Our data show that the majority of these genes were induced to higher levels when incubated with conditioned supernatants from late infection, with TLR3 and IFNα-2 being notable exceptions." (PMID 25798928, 2015). "Bioluminescence signals indicative of virus replication distinctly reveal the differences in the route of CHIKV dissemination in WT and Tlr3−/− mice during the initial phase of infection (Fig3C and Supplementary Videos S1 and S2)." (PMID 25452586, 2015). "TLR3 recognizes dsRNA and can influence disease outcomes depending on the type of virus and infection model." (PMID 25452586, 2015). "Given the obvious up-regulation of TLR3 mRNA expression by EIAVFDDV13 infection and the antiviral activity of type I interferons, changes in the expression of IFNβ and IFNα in eMDM after infection with EIAVFDDV13 and EIAVUK3 were evaluated." (PMID 25106750, 2014). "In the case of West Nile virus (WNV) infection, however, TLR3 plays a protective role against infection of neurons with this virus." (PMID 25101306, 2014). "In vitro infection of murine macrophages showed that LRV-Lae induced a TLR3-dependent inflammatory response as previously observed for LRV1." (PMID 24762979, 2014). "More importantly, infection resistance induced by EIAVFDDV13 is significantly reversed after TLR3 silencing." (PMID 25106750, 2014). "Our data indicate that besides the previous reported mechanism of competitive receptor binding by the viral surface protein, TLR3 pathway activation plays a vital role in the infection resistance induced by EIAVFDDV13 infection in macrophages in vitro." (PMID 25106750, 2014). "Intriguingly, pretreatment of NPSCs with poly IC, a synthetic analogue of double-stranded RNA known to interact with toll-like receptor 3, reduced the progression of infection as determined by “fluorescent timer” protein expression." (PMID 24722773, 2014). "This was dependent on TLR3 signalling, as shown by infection of macrophages from TLR3 knock-out mice." (PMID 24762979, 2014). "In this study, we show that IAV infection induces excessive expression of IFN-λ that is mainly dependent on RIG-I signaling and partially on TLR3 signaling, indicating that they are involved in the innate antiviral response to the infection." (PMID 24391501, 2014). "More importantly, TLR3 knockdown reversed the inhibition induced by EIAVFDDV13 to the level of 6 h of pre-infection." (PMID 25106750, 2014). "On the other hand, it was reported that TLR3−/− mice are more resistant to the infection with West Nile virus, indicating an important role of TLR3 in viral pathogenesis." (PMID 24860569, 2014). "In contrast to infection with LV, infection with Lena down-regulated the pathways involved in the interplay between the innate and adaptive immune response, cell death and TLR3/TLR7 signaling." (PMID 24643046, 2014). "Challenge-infection experiments in TLR3−/− animals have demonstrated that the immune response to viruses can be unaffected or impaired depending on the virus type." (PMID 24860569, 2014). "Here, we show that Toll-like receptor 3 (TLR3) expressed within uninfected hepatocytes is capable of sensing infection in adjacent cells, initiating a local antiviral response that partially restricts HCV replication." (PMID 23717201, 2013). "It is also possible that RV infection generates PAMPs that are sensed by other PRRs, such as TLR3, later in infection." (PMID 23894547, 2013).
infection (continued). "Influenza virus induced RIG-I (13 folds), MDA-5 (31 folds) and TLR3 (7.3 folds) at 12 h post infection." (PMID 23671700, 2013). "TLR3 expression was increased in mDCs, and this is likely related to infection of these cells since TLR3 is known to recognize dsRNAs." (PMID 23469297, 2013). "Mice with genetic deficiency of the homolog of MSR1 demonstrate increased susceptibility to infection with herpes simplex virus, while MSR1 is required for induction of TLR3-mediated signaling in monocytes exposed to human cytomegalovirus." (PMID 23717201, 2013). "This is in agreement with some previous studies that had also reported inhibition of infection of VSV-G-pseudotyped HIV-1 virions by TLR3 and TLR4 agonists (poly(I∶C) and LPS, respectively) in primary human myeloid cells." (PMID 23028330, 2012). "We assessed the effect of triggering TLR2, TLR3, TLR4, and TLR7 with selected ligands on the susceptibility of the J774A.1 macrophage cell line to infection with murine coronavirus (mouse hepatitis virus, [MHV])." (PMID 22754655, 2012). "In contrast, recovery of exudate macrophages from the airways of Myd88−/− or Tlr3−/− mice compared to C57BL/6 controls was similar 3 days after infection." (PMID 22496659, 2012). "Collectively, these findings support a role for cytosolic RLRs and TLR3 during host infection with intracellular bacterial pathogens." (PMID 22384131, 2012). "Conversely, the Toll-mutant Tlrv1/Tlr3 line showed a clear decrease in viability upon infection with S. aureus or R. oryzae, and DreddEP1412 flies were highly susceptible to P. aeruginosa." (PMID 22912810, 2012). "Accordingly, we also found less inflammation in the lungs of RV1B-infected MDA5−/− and TLR3−/− mice compared to control mice 24 h after infection." (PMID 21637773, 2011). "Meanwhile, using siRNA against TLR3 showed that down-regulation of TLR3 resulted in higher DV1 infection, and over-expression of TLR3 inhibited DV1 infection significantly by inducing high levels of IFN-β production." (PMID 21245912, 2011). "One of the pattern recognition receptors, TLR3, detects microbes including the influenza A virus that initiates the innate immune response against foreign pathogen infections." (PMID 21826229, 2011). "The ability of HAV to antagonize TLR3 signaling is likely to have evolved because antiviral responses evoked by TLR3 act in someway to restrict infection." (PMID 21931545, 2011). "By contrast, changes in the infected cells regarding expression of TLR3 molecule were observed as early as 6 h post-infection, with the maximum level occurring at 12 hours post-infection." (PMID 22206025, 2011). "To address these questions, we examined the airway responses of TLR3- and MDA5-deficient mice to infection with RV1B, a minor group virus which replicates in mouse lungs." (PMID 21637773, 2011). "The presumed ligand for TLR3 in infections with DNA viruses is dsRNA generated during bidirectional transcription of opposing DNA strands." (PMID 21994762, 2011). "Our data raise the possibility that TLR3- and MDA5-driven innate immune responses to RV, a relatively non-pathogenic virus, are maladaptive, at least at the onset of infection." (PMID 21637773, 2011). "Collectively, our results showed that RIG-I, MDA5 and TLR3 are able to recognize DV1 infection and establish a strong antiviral state in these cells." (PMID 21245912, 2011). "On the other hand, four days after infection, TLR3−/− mice showed significantly increased mRNA expression of IL-6, CCL2, CCL11 and IFN-λ." (PMID 21637773, 2011). "Control siRNA transfected cells showed increase in TLR3 expression upon DV1 infection as compared to siTLR3 transfected cells." (PMID 21245912, 2011). "This upregulation of TLR-3 following infection suggests a possible role for TLR-3 signaling in the innate recognition of RABV; however, TLR-3 activation needs to be further studied to conclusively define such a role." (PMID 20661430, 2010).
infection (continued). "Bacterial infection has also been shown to induce TLR3 mRNA expression in zebrafish and channel catfish, as well as in channel-blue backcross hybrids following infection with E. tarda and E. ictaluri." (PMID 20858287, 2010). "The importance of TLRs and particularly TLR3 following CB4 infection in vivo remains to be elucidated." (PMID 19122812, 2009). "The effect of infection on TLR3 levels was monitored by immunoblotting using two distinct antibodies (Ab) directed against the NH2 terminal of the TLR3 ectodomain (sc-Q18 and IMG-315A)." (PMID 19247444, 2009). "Taken together with the data presented in this report, this suggests that the TLR3-dependent production TNF-α plays a particularly important role in cardiac protection following infection with cardiotropic viruses." (PMID 19122812, 2009). "Further, multiple reports suggest that TLR3 signaling is either dispensable or even harmful following infection with other RNA viruses." (PMID 19122812, 2009). "In this study, we demonstrate that TLR3 signaling on macrophages is required for survival following CB4 infection." (PMID 19122812, 2009). "Blocking of TLR3 during infection impairs the antiviral response, resulting in increased rhinovirus replication." (PMID 19088911, 2008). "Infection with West Nile virus leads to a TLR3-dependent inflammatory response that mediates entry and penetration of the virus into the brain causing lethal encephalitis." (PMID 19088911, 2008). "Using microarrays it was shown that TLR3 is specifically induced upon infection of immature human monocyte-derived DCs with the attenuated poxvirus vector MVA." (PMID 19088911, 2008). "The R7041 infection increased TLR3 mRNA expression at 24 h p.i. when compared to HSV-1 (F)-infected cells (1 moi, P = 0.021)." (PMID 19025601, 2008). "The present study investigated the association of polymorphisms in the TLR3 gene (rs5743305 T/A and rs3775291 C/T) with HTLV-1 infection status and their relationship with infection-associated diseases, receptor expression levels, proviral load, and inflammatory and antiviral cytokines." (PMID 40831704, 2025). "Thus, although TLR3 is best studied as a detector of viral double-stranded RNA, it also plays a role in response to infections with various bacteria." (PMID 40362653, 2025). "TLR-3 expression was analyzed on the surface of myeloid cell subsets (CD11b+CD11c+), macrophages (CD11b+CD11c−), and lymphoid dendritic cells (CD11c+) from 6-, 36-, and 68-week-old mice at 2 days post-infection." (PMID 40732672, 2025). "Type of infection and gender influence on TLR3 SNP 1337 CT genotype distribution." (PMID 40299876, 2025). "We found that TLR2, TLR4, TLR9, and the TLR3/4 adaptor molecule TRIF are dispensable for inducing host resistance against the subsequent infection, as observed by reduced bacterial loads in the lung of mice that were first infected with Lp thyA L. pneumophila compared to mock." (PMID 40558085, 2025). "Upon infection, recognition of viral components by pattern recognition receptors, such as Toll-like receptor 3 (TLR3) and RIG-I-like receptors, activate signaling pathways that lead to the production of pro-inflammatory cytokines (e.g., IL-6 and TNF-α) and type I IFN." (PMID 41267781, 2025). "However, in an experiment carried out in another model, TLR3 was shown to be involved in cytokine production after infection with Chlamydia." (PMID 40362653, 2025). "This is further supported by the observation that increased levels of TLR3 in platelets and TLR5 in leukocytes correlate with severity of infection and survival, while increased levels of leukocyte TLR7 are associated with reduced severity of infection." (PMID 40825056, 2025). "Following infection with Poly (I:C), the ligand for macrophage TLR3 becomes activated." (PMID 39409044, 2024).
infection (continued). "After poly(I:C) infection, there was a downregulation of Uchl1 expression, while the expression of Tlr3, Caspase3, Caspase12, NOD-like receptor thermal protein domain associated protein 3 (Nlrp3), Interleukin-1β (IL-1β), IL-6, and Tumor necrosis factor alpha (Tnfα) was significantly upregulated." (PMID 38300431, 2024). "Viral titers performed on bile ducts harvested from WT-BALB/c and TLR3 KO mice 7 and 10 days post-RRV infection demonstrated equal infection at day 7 while day 10 post-RRV-infected TLR3 KO mice have significantly higher viral titers than WT-BALB/c mice, indicating an ongoing, unregulated viremia." (PMID 38860860, 2024). "Additionally, vaccine binding affinity with TLR2 and TLR3, which play a crucial role in M. tuberculosis protection following infection, demonstrated that all models elicit a good immune response." (PMID 39624097, 2024). "Moreover, the serum titles of SEA-specific IgMs and IgGs decreased significantly in TLR3 KO mice compared with WT mice during infection." (PMID 38172683, 2024). "Murine macrophages and fibroblasts were reported to produce type I IFNs following infection by a few atypical T. gondii strains and the related parasite Neospora caninum, depending on endosomal TLRs, particularly TLR3, and cytoplasmic receptor RIG-1, respectively." (PMID 36839591, 2023). "Treatment with melatonin at 250 μM before and after infection significantly reversed the induction of TLR3 (p < 0.05) and TLR7 (p < 0.01) mRNA levels and suppressed the expression of NF-κB (p < 0.05), COX-2 (p < 0.05) and TNF-α (p < 0.001) induced by JEV infection." (PMID 37055489, 2023). "Furthermore, the dependence on Toll-like receptors for the activation of autophagy in the control of L. major infection was proven using TLR3, -7, and -9 knockout (Tlr3/7/9−/−) mouse macrophages, which are incapable of infection control." (PMID 37064813, 2023). "We next assessed whether TLR3 stimulation increased MYADM expression as we observed with live RV1B infection." (PMID 37638015, 2023). "Transcriptional analyses of infected cells have shown how MPOX infection avoids detection by TLR3." (PMID 37533932, 2023). "Furthermore, the transcription of TLR3 in spleen and kidney showed a change pattern with a wave shape after the poly (I:C) infection." (PMID 36670828, 2023). "For example, co-administration of TLR3 agonists with SARS-CoV-2 protects mice from infection." (PMID 37854858, 2023). "In addition, the transcription levels of TLR3 were significantly increased in immune-related tissues after infection of exogenous Aeromonas hydrophila and poly (I:C)." (PMID 36670828, 2023). "Indeed, while the ability of TLR3 to trigger type I IFN synthesis has been demonstrated in certain cell models following infection by DENV, the results obtained with other flaviviruses, in particular ZIKV or WNV, are less clear." (PMID 37965539, 2023). "By trend, we found an induction of TLR3 when poly I:C was applied 12 h before RV-A1b infection." (PMID 38140569, 2023). "Inborn errors of IRF7- and TLR3-dependent type I IFN immunity cause life-threatening COVID-19 pneumonia in patients without prior severe infection." (PMID 37006316, 2023). "TLR3 is a member of a family of immune receptors that are crucial for activating the innate immune response, indirect activation of the adaptive immune system, and control of cytokine expression in the defense of the body against infections." (PMID 37510216, 2023). "Upon meeting with viral pathogens, intestinal epithelial cells initiated mucosal immune responses to prevent infection by activating innate pathways, such as the TLR3 signaling pathway, which stimulate the production of type I IFNs and inflammatory cytokines that recruit and activate immune cells." (PMID 37372583, 2023). "In general, TLR3 activation has an anti-viral effect by triggering innate anti-viral immunity and the secretion of pro-inflammatory cytokines, thereby recruiting immune cells to combat the infection." (PMID 36851477, 2023).
infection (continued). "Interestingly, the transcription of hybrid yellow catfish TLR3 changed significantly after the infection of exogenous A. hydrophila, and the most sensitive tissues included spleen and kidney." (PMID 36670828, 2023). "Moreover, CSE significantly downregulated c-c motif chemokine 5 (CCL5) and Toll-like receptor 3 (TLR3) while these genes were upregulated upon Sp only infection (cluster 1 and 5)." (PMID 35681466, 2022). "Infection experiments were performed using homozygous C57BL/6J-derived MyD88 (-/-) knock-out (MyD88 KO) mice deficient in signaling of all TLRs through the MyD88 adaptor and retaining only the TRIF-mediated endosomal TLR4 and TLR3 signaling pathways." (PMID 35395059, 2022). "The role of TLR3 in MRV’s infection requires further studies, as its involvement is still unclear." (PMID 36560714, 2022). "Interestingly, NLRP3 inflammasome together with FcγRIII, TLR3, and antiplatelet antibodies contribute to the induction of hemorrhage during secondary infection with DENV." (PMID 36016430, 2022). "Regardless, future studies should delineate the viral proteins that may interact with TLR3 within the CNS using primary neuron cultures or neuron-like cell lines with various routes of infection and at multiples times post-infection." (PMID 35409387, 2022). "During infection, type 1 IFNs could be induced through the recognition of viral RNA by the host pattern-recognition receptors TLR3, RIG-I, and MDA-5." (PMID 36125898, 2022). "Consistently, TLR3 activation by poly I:C, a synthetic dsRNA used to mimic viral nucleic acids and model innate immune responses, improves the survival of aged mice and reduces pathological changes and viral loads in the lungs following infection with MA15." (PMID 36419185, 2022). "The innate immunity responses, including type I and III interferon (IFN-β, IFN-κ, IFN-λ1), ISG (ISG54, MxA, MxB) and TLR3 mRNA expression, were studied at 8, 24 and 48 hours post transfection, which equal to 4, 20 and 44 hours post infection (hpi), respectively." (PMID 35793357, 2022). "First, we have found that the presence in a homozygous state of the alternative allele of TLR3 (rs3775291) (TT genotype) exerts a protective role on the risk of CMV viremia at any level and, with borderline significance, at high-level (≥1,000 IU/ml) infection." (PMID 35967300, 2022). "Importantly, TLR3/RLR inhibition in bat organoids significantly boosted viral growth in the early phase after SARS-CoV-2 or CoV-HKU4 infection." (PMID 36529763, 2022). "Deficiency of Yap in mice also resulted in transcriptional upregulation of Tlr3, and elevated activation of Irf3 signaling in lung tissue upon infection, which was accompanied by a reduction in viral nucleocapsid (NP) protein expression upon infection." (PMID 35503798, 2022). "After 12 h of infection, the mRNA levels of TLR3 returned comparable to control." (PMID 35732858, 2022). "After infection viral genetic material connects with TLR-3, which induces IFN production." (PMID 35745512, 2022). "Furthermore, we demonstrated here that NV1505 and PG1505 can enhance the response against S. pneumoniae secondary infection up to 30 days after the TLR3-mediated inflammation." (PMID 36363777, 2022). "TLR3 was also found in Leishmania-containing phagosomes at different time points of infection." (PMID 35154115, 2022). "After 9 h of infection, an upregulation of TLR3 mRNA was observed compared to control, while the CHEK2 mRNA could not be detected in THP-1 cells exposed to WN stool sample." (PMID 35732858, 2022). "Previous studies showed that the expression of TLR1/3/7/8 were repressed strongly at 8 weeks post-infection during the course of Schistosoma infection, especially TLR3, and the expression of TLR1/2/4/9 were decreased on B cells and monocytes after filarial infection." (PMID 35739856, 2022).